SOX9 (SRY-box transcription factor 9)
Diseases named in the same sentence as SOX9 in open-access papers (continued):
Sharing a sentence is not in itself a finding about the gene and the disease.
skin aging (1 paper, 2022). The gradual irreversible changes in structure of skin that occur as a result of the passage of time.. "Our results can provide effective evidence that Sox9 and claudin 2 are involved in the process of skin aging." (PMID 35965621, 2022). "In addition, claudin 2 and SOX9 have similar effects on skin aging related factors." (PMID 35965621, 2022).
Sotos syndrome (1 paper, 2023). Sotos syndrome is a rare multisystemic genetic disorder characterized by a typical facial appearance, overgrowth of the body in early life with macrocephaly, and mild to severe intellectual disability. "In humans, heterozygous loss-of-function variants in NSD1 increase skeletal growth in Sotos syndrome, whereas, in mice, homozygous loss of Nsd1 impairs skeletal growth, in part by regulating Sox9 expression in chondrocytes." (PMID 36927955, 2023).
spina bifida (1 paper, 2022). A congenital neural tube defect in which vertebrae are not fully formed. "Our results further support this evidence as Sox9, Notch1, and BMP2/4 gene expression was upregulated at the time of early astrogliosis in spina bifida, and BMP2/4 expression with S100b and Aldh1l1, an early astrocyte markers." (PMID 35782393, 2022). "Furthermore, we present the involvement of Notch1, Sox9, and BMP signaling in NPC cell fate during gestation and their role in self-propelling earlier astrogliosis observed in spina bifida." (PMID 35782393, 2022).
Spina bifida occulta (1 paper, 2015). The closed form of spina bifida with incomplete closure of a vertebral body with intact overlying skin. "He had no skeletal abnormalities except for spina bifida occulta, a relatively common neural tube anomaly of that has not been associated with SOX9 mutations." (PMID 26740947, 2015).
sweat gland carcinoma (1 paper, 2024). A carcinoma arising from the sweat glands. "This study documents the first case of endocrine mucin-producing sweat gland carcinoma (EMPSGC) in a dog, successfully differentiating it from other apocrine gland tumors and MGC using immunohistochemical markers such as CK19, Sox9, CK5, p63, and vimentin." (PMID 39765541, 2024).
Tetralogy of Fallot (1 paper, 2018). A congenital cardiac malformation comprising pulmonary stenosis, overriding aorta, ventricular septum defect, and right ventricular hypertrophy. "CD patients, as well as individuals with mutations in the SOX9 promoter and 5′UTR, have been reported to have a number of congenital heart and great vessel defects including Tetralogy of Fallot, ventricular and atrial septal defects, patent foramen ovale, and aortic stenosis." (PMID 30224706, 2018).
thanatophoric dysplasia type 2 (1 paper, 2024). Thanatophoric dysplasia characterized by a cloverleaf-like skull and straight femurs. "In mice expressing the thanatophoric dysplasia type II activating FGFR3 mutation, the defect in chondrocyte maturation and bone formation was linked to increased SOX9 protein stability." (PMID 38885336, 2024).
thymic tumor (1 paper, 2021). "However, the precise mechanism of SOX9 in the initiation and progression of TETs were not well investigated in this study, due to a lack of thymic tumor cell lines and the unavailability of animal models of thymic tumors." (PMID 34778027, 2021).
tumor (534 papers, 1999 to 2026). "Functional validation via CD44 knockdown and in vivo xenograft assays confirmed that the COL1A1-CD44 axis mediates SOX9 mutation-driven stemness maintenance and tumor progression." (PMID 42218401, 2026). "Previous studies have shown that SOX9 promotes immune evasion by secreting LIF to regulate tumor‐associated macrophage polarization and inhibit CD8+ T‐cell function, highlighting its central role in shaping an immunosuppressive microenvironment." (PMID 41270217, 2026). "Loss of SOX9 decreases tumor burden, extends survival and enhances anti-tumor immunity by increasing levels of tumor-infiltrating dendritic cells and CD8+ T cells." (PMID 41268614, 2026). "Collectively, our results indicate SOX9 can function as a tumor suppressor factor in colon tumorigenesis, and SOX9 loss promotes tumor progression in part by augmenting epithelial-mesenchymal transition (EMT) and cancer stemness phenotypes." (PMID 40179020, 2025). "The functional role of HEY1-NCOA2 was further explored using the histone deacetylase (HDAC) inhibitor panobinostat, which inhibited HEY1-NCOA2-associated gene expression (Sox9, Runx1, Hes1) and tumor growth in xenograft models." (PMID 40867318, 2025). "In closing, to our knowledge our study is among the first to link SOX9 loss to enhanced tumor aggressiveness and progression in CRC development in in vivo models and in patients." (PMID 40179020, 2025). "Our analysis showed that positive SOX9 expression and intensity scores were significantly associated with tumor size, differentiation, vascular and perineural invasion, and the presence of lymph node and distant metastases." (PMID 39907598, 2025). "Activation of integrin signaling is often associated with tumorigenesis and tumor invasion, as is ephrin signaling, GTPase signaling, and the predicted activated upstream regulator SOX9." (PMID 40316897, 2025). "Prolonged activation of SOX9 selectively engages tumor-associated enhancers, promoting the malignant transformation of normal cells." (PMID 40032852, 2025). "About 20% of 171 human CRCs showed loss of SOX9 protein expression, which correlated with higher tumor grade." (PMID 40179020, 2025). "Transcription factors (TFs) associated with tumor metastasis and progression, such as SOX9, HMGA2, TP63, NFIL3, and IRF6, exhibited high transcriptional activity in the ITGA2hi‐PTC subcluster." (PMID 40985182, 2025). "Lately SOX2 and SOX9, transcription factors associated with stemness‐like phenotypes of cancer cells, have been linked to tumor growth, metastasis, and resistance to therapy." (PMID 39180200, 2025). "Our findings demonstrated that IRF4‐mediated SOX9 induction in BCL2‐overexpressing DLBCL was associated with tumour progression, suggesting the potential therapeutic implication of the IRF4‒SOX9 signalling axis in this type of DLBCL." (PMID 40356256, 2025). "SOX9 somatic mutations are found in about 5%–10% of human CRCs, and most mutations are frameshift or nonsense, suggesting a possible tumor suppressor role of SOX9 in CRCs." (PMID 40179020, 2025). "Tumours with SOX9 or TCF7L2 mutations had increased expression of the respective genes, while other mutant WNT pathway drivers had reduced tumour expression." (PMID 39112715, 2024). "This study explores the inverse association of SOX2/SOX9 and their distinct expression in tumors, influencing the tumor microenvironment and radiotherapy responses." (PMID 38275880, 2024). "Inha KO somatic cell tumours lack SOX9, a key hallmark feature of adult Sertoli cells and exhibit an unexpected steroidogenic profile, while providing a microenvironment that supports SSC self-renewal." (PMID 37564373, 2023). "By inspecting their oncoprint, 27/59 tumours harboured mutations in either SOX9 or MYC and were wild-type in either BRAF, KRAS or NRAS, hinting towards an alternative cetuximab resistance mechanism." (PMID 37666855, 2023).
tumor (continued). "Previous data suggest that dormant disseminated tumor cells not only undergo a deep growth arrest but also exhibit an upregulation of genes associated with self-renewal and pluripotency, including Sox9, Oct4, Sox2, and Nanog." (PMID 37958610, 2023). "YAP and SOX9 expression are associated with tumor progression and poor prognosis and survival in patients with HCC and CCA, suggesting a potential role as predictive and prognostic markers in patients with PLC." (PMID 37627221, 2023). "Of note, TGFβ signaling was shown to promote EMT, which is manifested by the loss of E-Cadherin and increased expression of SOX9 and Vimentin, thus promoting tumor invasion in NSCLC." (PMID 37085672, 2023). "Recent evidence suggests that SOX9 is associated with clinical tumor-node-metastasis stage and it can stimulate the malignant biological characteristics of NSCLC in vitro." (PMID 36182943, 2022). "EMT is manifested by the loss of E-cadherin and increased expression of Vimentin and SOX9, thus promoting tumor invasion." (PMID 35688943, 2022). "Next, our analysis implicated that the overexpression of SOX9 was obviously correlated with tumor stage (OR = 0.48; 95% CI: 0.20–1.12; P = .04) and lymph node metastasis (OR = 0.36; 95% CI: 0.19–0.67; P = .0010)." (PMID 36123852, 2022). "The upregulated of SOX9 was associated with the tumor occurrence, invasion, metastasis, and poor patient survival rate." (PMID 35281088, 2022). "Transcriptomic dataset analysis demonstrated that tumor-derived PRDM1 was positively associated with expression of Sox-9, a well-known modulator of cancer progenitor cells in CRC." (PMID 33972671, 2021). "EGFR wild type is associated with decreased expression of BMX/SOX9 and inadequate pericyte coverage in neovascularization, and such an incomplete vascular system exacerbates tumor tissue hypoxia and necrosis." (PMID 34566988, 2021). "The over-expression of SOX9 had a significant impact on GH-secreting adenomas tumor incidence with the odds ratio of 8.4 and the diagnostic value of SOX9 was considerable." (PMID 33736633, 2021). "In the present study, the delayed tumor burden and onset in the Sox9-Pten compared to the Alb-Pten mice suggest that PTEN loss in SOX9+ cells alone can drive the biliary hyperplasia phenotype but additional signals are needed for tumor promotion." (PMID 34083580, 2021). "We performed immunohistochemistry (IHC) staining of tumor-specific SE-associated transcription factor SOX9 on patient tissue samples and found that higher level of SOX9 was observed in tumors than adjacent normal lung tissues." (PMID 34001209, 2021). "Compared to the previously reported Alb-Pten (PtenloxP/loxP; Albumin-Cre+) mice that carry PTEN loss in all hepatocytes, the incidence of tumor formation in Sox9-Pten mice was significantly lower." (PMID 34083580, 2021). "In this way, we found that a number of well-known oncogenes, including MYC and SOX9, were annotated as targets of tumor-specific SEs, while several tumor suppressor genes in LUAD, such as DLC1 and RB1, were linked to normal-specific SEs." (PMID 34001209, 2021). "We observed differential activation of tumor associated macrophages, with patients with high SOX9 expression had enrichment of M2 macrophages." (PMID 34778027, 2021). "As per previous reports, SOX9 guides signaling implicated in tumor initiation, metastasis, cancer cell proliferation, chemo- and radio-resistance, and stem cell maintenance, thereby affecting tumorigenesis as an oncogene." (PMID 35083143, 2021). "Disturbing this regulation implies a high risk of tumor development as SOX9 is involved as an oncogene in various types of cancer, but it can also act as a tumor suppressor in other tumor entities." (PMID 33076370, 2020). "Our results highlight the function of SOX9 in controlling multiple processes associated to cancer and, hence explaining, how SOX9 potentiates tumor progression not only regulating the activity of CSCs." (PMID 31941916, 2020).
tumor (continued). "It is likely a pro-oncogene, as high SOX9 expression has been linked to advanced tumor stage and adverse prognosis in primary CRC." (PMID 31337155, 2019). "We also evaluated the expression of biliary marker Sox9; expression of biliary markers has been associated with less differentiated tumor types." (PMID 30863496, 2019). "The overexpression of SOX9 caused neoplasia and promoted invasion of tumor in prostate of murine models in the same way as ERG." (PMID 31027362, 2019). "Our previous work had shown that Sox9 can promote tumour initiation in mice with a heterozygous Pten mutation." (PMID 29484136, 2018). "Several studies have shown that SOX9 is differently expressed in many types of cancer, such as urothelial cancer, prostate cancer and lung cancer and is associated with tumor initiation and progression." (PMID 28356064, 2017). "Because of its involvement in these processes, SOX9 is likely to be causally involved in tumor progression and, consequently, increased levels of SOX9 would be expected to indicate a poor prognosis." (PMID 29348895, 2017). "By statistical correlation, Sox9 upregulation is associated with venous invasion and advanced tumor stage." (PMID 27105493, 2016). "Upregulation of Sox9 transcript level was associated with poorer tumor cell differentiation (p = 0.003), venous invasion (p = 0.026), advanced tumor stage (p = 0.044) and shorter overall survival (p = 0.042)." (PMID 27105493, 2016). "The distribution and nature of SOX9 mutations in CRC is similar to that seen in classic tumor suppressors, namely mostly truncating mutations across the length of the gene without hotspots." (PMID 27248473, 2016). "Here, reduced SOX9 expression was strongly linked to advanced tumor stage, high Gleason grade, high preoperative PSA levels, presence of nodal metastases (p<0.0001 each) and positive surgical margin (p = 0.001)." (PMID 26030748, 2015). "Surprisingly, 58% (11/19) of the genes downregulated by SOX9 were associated with improved survival, which strongly suggests SOX9 represses a set of genes that decrease tumor malignancy." (PMID 25885555, 2015). "Our findings disagree with some previously published studies reporting SOX9 expression in the normal and tumor-associated melanocytic lineage." (PMID 25629959, 2015). "Reduced SOX9 expression was linked to an unfavorable tumor phenotype, including late stage, high Gleason grade, and elevated preoperative PSA levels (p<0.0001 each) in all cancers." (PMID 26030748, 2015). "In vivo, sox9 expression in B16F1 cells increases their metastatic potential causing more tumor lung nodules in the tail vein injection assay." (PMID 25885555, 2015). "Pan-CK and SOX9 are markers of stem cell activation, which have been implicated in tumor pathogenesis." (PMID 24080367, 2013). "The expression of Sox9 was upregulated in hepatocellular carcinoma and lung adenocarcinoma, and it was associated with tumor progression and poor prognosis of the diseases." (PMID 23443092, 2012). "A significant association of hypermethylation with tumour grade was found for SOX9 (Mann–Whitney, P=0.032)." (PMID 18087279, 2008). "In addition, SOX9 modulates the expression of mediator of DNA damage checkpoint 1and minichromosome maintenance complex components, which are associated with tumor cell proliferation, invasion and metastasis." (PMID 41268614, 2026). "Our findings support a tumor suppressor role for Sox9 in Apc mutation–dependent tumorigenesis." (PMID 40179020, 2025). "Indeed, the subgroup of tumors with high SOX2 but low SOX9 expression (SOX2highSOX9low) was significantly associated with a smaller tumor size (p < 0.042) and lower probability for lymph node metastasis (p < 0.026)." (PMID 39180200, 2025). "Furthermore, our results indicated biallelic inactivation of Sox9 in the A or AKP models was associated with higher tumor grades and enhanced invasiveness and metastasis." (PMID 40179020, 2025).
tumor (continued). "In addition to its involvement in tumor immune evasion and tissue repair mechanisms, SOX9 is implicated in various immune-related disorders." (PMID 41293317, 2025). "Complementary single-cell-ST atlases corroborate a chemoresistance-associated peri-vascular niche populated by SOX9+ stem-like tumour cells and immunoregulatory CAF subsets expressing CXCL12, illuminating how spatial confinement coordinates lineage plasticity and immune suppression." (PMID 40740859, 2025). "Our results indicate SOX9 has tumor suppressor function in CRC; its loss may promote progression, invasion, and poor prognosis by enhancing EMT and stem cell phenotypes." (PMID 40179020, 2025). "Loss of SOX9 protein expression was associated with increased tumor-grade." (PMID 40179020, 2025). "Overall, our findings from in-depth analysis of the TCGA data bolster the view that SOX9 functions as a tumor suppressor in a notable subset of human CRCs, with loss of SOX9 expression and function promoting tumor progression and invasion and poorer patient outcomes." (PMID 40179020, 2025). "Moreover, overexpression of SOX9 alleviated the tumour growth inhibition and prolonged survival caused by USP18 depletion." (PMID 40374599, 2025). "Consequently, SOX9 is widely regarded as an oncogene and is significantly implicated in tumor chemoresistance and malignant potential." (PMID 41293317, 2025). "SOX9 expression loss in human CRCs is linked to higher tumor grade and epigenetic silencing." (PMID 40179020, 2025). "Our findings further support a tumor suppressor role for Sox9 in Apc mutation–dependent tumorigenesis, with combined Sox9 and Apc biallelic inactivation leading to lesions with high-grade dysplasia and invasion typical of carcinoma, as well as an apparent block to intestinal differentiation." (PMID 40179020, 2025). "Interestingly, we also observed that reduced expression of SOX9 rescued the increased tumour burden and decreased survival caused by USP18 overexpression." (PMID 40374599, 2025). "However, prolonged SOX9 activation selectively engages tumor-associated enhancers, leading to the activation of the Wnt/β-catenin signaling pathway." (PMID 40032852, 2025). "The loss-of-function mutations suggest a presumptive tumor suppressor role for SOX9 in CRC." (PMID 40179020, 2025). "Considering their essentiality to the onset of aberrant stem-like gene expression and subsequent tumor initiation in the colonic epithelium, development-associated factors (e.g., Sox9) are now also proposed as prospective therapeutic targets to block tumorigenesis at the root." (PMID 37894295, 2023). "The high expression of SOX9 was associated with tumor progression and linked with overall survival." (PMID 36123852, 2022). "Besides, SOX9 protein regulates various pathways which are associated with tumor initiation, growth, metastasis, and chemoresistance." (PMID 35395444, 2022). "Besides, our analysis demonstrated that the strong associations of SOX9 with age, tumor size, histological differentiation, tumor stage, lymph node metastasis and TNM stage in GC patients." (PMID 36123852, 2022). "Our results concluded that GC patients with high SOX9 levels had a poor OS compared those with low SOX9 levels, meanwhile, positive SOX9 expression was significantly linked with age, tumor size, histological differentiation, tumor stage, lymph node metastasis and TNM stage." (PMID 36123852, 2022). "Then, we ranked all the TFs and found SOX9 was ranked as top one tumor-specific SE-associated TF." (PMID 34001209, 2021). "Finally, we demonstrate that Wnt/β-catenin serves as the synergistic signal that promotes the proliferation of and tumor formation from the PTEN loss transformed SOX9+ liver TICs." (PMID 34083580, 2021). "Sox9 overexpression was associated with higher tumor grade, stage and poorer survival in HCC." (PMID 33112555, 2020).